SMAD5 (SMAD family member 5)
Description:
Transcriptional regulator that plays a role in various cellular processes including embryonic development, cell differentiation, angiogenesis and tissue homeostasis. Upon BMP ligand binding to their receptors at the cell surface, is phosphorylated by activated type I BMP receptors (BMPRIs) and associates with SMAD4 to form a heteromeric complex which translocates into the nucleus acting as transcription factor. In turn, the hetero-trimeric complex recognizes cis-regulatory elements containing Smad Binding Elements (SBEs) to modulate the outcome of the signaling network. Non-phosphorylated SMAD5 has a cytoplasmic role in energy metabolism regulation by promoting mitochondrial respiration and glycolysis in response to cytoplasmic pH changes. Mechanistically, interacts with hexokinase 1/HK1 and thereby accelerates glycolysis.
Synonyms: MADH5; Dwfc; JV5-1
Tractability: PROTAC: ubiquitination databases record sites on it.
Gene: Protein-coding gene on chromosome 5 (136,132,845 to 136,188,747, forward strand). Ensembl gene ENSG00000113658.
Subcellular location: Cytoplasm; Nucleus; Mitochondrion
Subcellular location (Human Protein Atlas): Nucleoplasm; Cytosol
Pathways (Reactome):
Signal Transduction: Signaling by BMP
Gene Ontology:
Molecular function: DEAD/H-box RNA helicase binding; protein binding; RNA polymerase II cis-regulatory region sequence-specific DNA binding; sequence-specific double-stranded DNA binding; ubiquitin protein ligase binding; DNA-binding transcription factor activity; DNA-binding transcription factor activity, RNA polymerase II-specific; I-SMAD binding; DNA-binding transcription repressor activity, RNA polymerase II-specific; RNA polymerase II transcription regulatory region sequence-specific DNA binding
Biological process: anti-Mullerian hormone receptor signaling pathway; BMP signaling pathway; cell differentiation; intracellular iron ion homeostasis; negative regulation of apoptotic process; negative regulation of Fas signaling pathway; negative regulation of gene expression; osteoblast differentiation; positive regulation of osteoblast differentiation; anatomical structure morphogenesis; cardiac conduction system development; embryonic pattern specification; positive regulation of DNA-templated transcription; positive regulation of transcription by RNA polymerase II; regulation of transcription by RNA polymerase II; signal transduction; SMAD protein signal transduction; stem cell differentiation; transforming growth factor beta receptor signaling pathway; cellular response to growth factor stimulus; developmental process; Mullerian duct regression; negative regulation of transcription by RNA polymerase II; ossification; regulation of DNA-templated transcription; and 2 more
Cellular component: cytoplasm; cytosol; mitochondrion; nucleoplasm; nucleus; protein-containing complex; chromatin; heteromeric SMAD protein complex; SMAD protein complex; transcription regulator complex
Genetic constraint (gnomAD): Loss-of-function variants: 1 observed, 27.3 expected, observed/expected ratio (o/e) 0.0366, 90% interval 0.012 to 0.17. The upper end of that interval is the gene's LOEUF score, 0.17, which puts it in group 1 of 6, group 1 being the genes least tolerant of losing a copy. Missense variants: 231 observed, 414.5 expected, observed/expected ratio (o/e) 0.56, 90% interval 0.5 to 0.62. Synonymous variants: 145 observed, 144.71 expected, observed/expected ratio (o/e) 1, 90% interval 0.88 to 1.15.
Homologues: Orthologues: chimpanzee SMAD5 (100% identical), dog SMAD5 (100% identical), macaque SMAD5 (100% identical), pig SMAD5 (100% identical), guinea pig SMAD5 (99% identical), rabbit SMAD5 (99% identical), rat Smad5 (99% identical), mouse Smad5 (99% identical), zebrafish smad5 (91% identical), Caenorhabditis elegans daf-14 (20% identical). Paralogues in human: SMAD1 (91% identical), SMAD9 (78% identical), SMAD2 (61% identical), SMAD3 (61% identical), SMAD4 (41% identical), SMAD6 (26% identical), SMAD7 (24% identical).
Diseases named in the same sentence as SMAD5 in open-access papers:
SMAD5 is named in the same sentence as 85 diseases in open-access papers, as found by Europe PMC text mining. Sharing a sentence is not in itself a finding about the gene and the disease. The quoted sentences say what the papers report.
breast cancer (20 papers, 2014 to 2024). A primary or metastatic malignant neoplasm involving the breast. "We demonstrate for the first time the causal role of Aurora-A/SMAD5 oncogenic axis in the development of endocrine resistance through down-regulation of ERα expression in initially ERα+ breast cancer cells." (PMID 24816249, 2014). "SMAD4, SMAD2, SMAD3, SMAD7, SMAD1, SMAD6, and SMAD5 showed genetic variation in 1.8%, 1.2%, 1.1%, 0.8%, 0.7%, 0.6%, and 0.5% of patients with breast cancer, respectively." (PMID 38514720, 2024). "The analysis showed a significant increase in the concentration of SMAD3, SMAD4, and SMAD5 in all types of breast cancer samples compared to the control." (PMID 39337574, 2024). "Breast cancer cells promote the expression of SMAD5 in γδT cells through the transfer of the lncRNA, SNHG16, in exosomes, which functions as a ceRNA through miR-16-5p, thereby enhancing the TGF-β1/Smad5 pathway and upregulating CD73 expression." (PMID 34295338, 2021). "Breast cancer-derived exosomes transmit SNHG16 to induce CD73+ γδ1 Treg cells by activating the TGF-β1/SMAD5 pathway." (PMID 34295338, 2021). "Mechanistically, TEM8 increases active RhoC level and induces ROCK1-mediated phosphorylation of SMAD5, in a cascade essential for promoting stemness and VM capacity of breast cancer cells." (PMID 34285210, 2021). "We demonstrate that SMAD5 expression is required to induce a CD44+/CD24-/ALDH1+ breast cancer stem cell-like phenotype, suggesting that the Aurora-A/SMAD5 axis promotes chemoresistance through activation of stemness signalling in breast cancer." (PMID 29207686, 2017). "In this study, we defined the role of the Aurora-A/SMAD5 oncogenic axis in the induction of chemoresistance in breast cancer cells." (PMID 29207686, 2017). "Because expression of the CD44 stemness marker promotes chemoresistance in breast cancer cells, we investigated the extent to which SMAD5 activity was required to induce CD44 expression in MDA-MB 231 cells." (PMID 29207686, 2017). "Significantly, SMAD5 expression was required to induce chemoresistance and maintain a breast cancer stem cell-like phenotype, indicating that the Aurora-A/SMAD5 oncogenic axis promotes chemoresistance through activation of stemness signaling." (PMID 29207686, 2017). "Here we define the role of the Aurora-A kinase in the induction of chemoresistance of breast cancer cells through phosphorylation and activation of SMAD5." (PMID 29207686, 2017). "We demonstrate for the first time the causal role of the Aurora-A mitotic kinase in the development of endocrine resistance through activation of SMAD5 nuclear signaling and down-regulation of ERα expression in initially ERα+ breast cancer cells." (PMID 24816249, 2014). "SMAD3 and SMAD5 were overexpressed in all types of breast cancer, which could be related to the reduced expression of miR-145, and the findings for SMAD4 and miR-155 were similar." (PMID 39337574, 2024). "In breast cancer, resistance to paclitaxel can be reversed with the depletion of SMAD5." (PMID 35805024, 2022). "This contribution is highly significant for the treatment of endocrine refractory breast carcinomas, because it may lead to the development of novel molecular therapies targeting the Aurora-A/SMAD5 oncogenic axis." (PMID 24816249, 2014). "This contribution is important for the treatment of endocrine refractory breast carcinomas, because it may lead to the development of novel molecular therapies targeting the Aurora-A/SMAD5 oncogenic axis." (PMID 24816249, 2014). "LncRNA SNHG16 is transmitted by breast cancer-derived exosomes and initiates CD73 expression in γδ1 Tregs by sponging miR-16-5p and inducing SMAD5." (PMID 37346034, 2023). "LncRNA SNHG16/miR-16-5p/SMAD5-regulatory axis potentiates TGF-β1/SMAD5 pathway activation, thus inducing CD73 expression in Vδ1 T cells in breast cancer-derived exosomal." (PMID 35812382, 2022).
breast cancer (continued). "In addition to stimulating Smad1, Smad5 and Smad8 phosphorylation and nuclear translocation, BMP7 also induces Smad3 phosphorylation and nuclear accumulation in breast cancer cells and silencing Smad3 abrogates BMP7-induced telomerase inhibition." (PMID 27696331, 2017). "Taken together, these findings reveal a novel mechanism of drug resistance and provide the preclinical rationale to developstrategies that target the non-canonical Aurora-A/SMAD5 oncogenic axis and restore chemosensitivity in breast cancer cells." (PMID 29207686, 2017). "Taken together, these findings identified a novel mechanism of drug resistance through aberrant activation of the non-canonical Aurora-A/SMAD5 oncogenic axis in breast cancer." (PMID 29207686, 2017). "In the last step, miRNA microarray analysis was performed to identify differentially expressed miRNAs in each breast cancer subtype, and then it was determined whether they could participate in the regulation of the expression of SMAD3, SMAD4, SMAD5, and SMAD7 selected in previous steps." (PMID 39337574, 2024). "Moreover, among them, the exosomal lncRNA SNHG16 secreted by breast cancer (BC) cells can specifically increase CD73 expression on Vδ1 Treg cells, which are the predominant regulatory T-cell population in BC through the SNHG16/miR-16-5p/SMAD5 regulatory axis." (PMID 36979019, 2023). "Long noncoding RNA (lncRNA) small nucleolar RNA host gene 16(SNHG16), mediated by exosomes, could sponge miR-16-5p to upregulate SMAD family member 5(SMAD5), resulting in cluster of differentiation 73(CD73) upregulation in Vδ1 T cells, promoting the immunosuppressive regulations in breast cancer." (PMID 37476905, 2023). "Moreover, lncRNA SNHG16 transmitted by exosomes is also proved to induce CD73+γδ1 Treg in breast cancer by sponging miR-16-4p, which enables the downregulation of SMAD5, the subsequent enhancement of TGF-b1/SMAD5 pathway, and finally, the promotion of CD73 expression." (PMID 34616851, 2021). "Furthermore, SMAD5 phosphorylation induced by an aberrant Aurora-A kinase activity, led to its nuclear activation and ultimately contributed to the development of EMT, stemness and tumor progression in human breast cancer cell line MCF-7." (PMID 27581651, 2016). "SMAD5 appeared up-regulated but not Aurora kinase A (AURKA), which cooperates to promote chemoresistance in breast cancer therapies." (PMID 36430510, 2022). "On the other hand, Reverse Phase Protein Array (RPPA) data for the breast cancer patient cohort, where it is possible to analyze the change in β-CATENIN protein level, did not include either BMP2/BMP6 or phosphorylated SMADs (SMAD1/SMAD5) or direct target genes of BMP pathway such as ID1–3." (PMID 38731813, 2024).
gastric cancer (8 papers, 2021 to 2025). A primary or metastatic malignant neoplasm involving the stomach. "Since Smad5 has been suggested as an oncogene in several tumors including Epstein–Barr virus (EBV)-associated gastric cancer." (PMID 33911345, 2021). "In other cancers, high SMAD5 levels promoted poorer overall survival in gastric cancer, shorter survival in lymphatic leukemia, and bladder cancer progression." (PMID 39337574, 2024). "Analysis showed that high expression levels of SMAD1, SMAD2, and SMAD4 are associated with a better survival rate of gastric cancer patients, whereas SMAD3, SMAD5, SMAD6, SMAD7 and SMAD9 are associated with poor prognosis." (PMID 34138687, 2021). "On the other hand, SMAD3, SMAD5, SMAD6, and SMAD7 were associated with poor OS in the second and third stage of gastric cancer." (PMID 34138687, 2021). "In addition, the expression of SMAD5 has been shown to be positively correlated with the tumour grade of gastric cancer." (PMID 40852585, 2025).
glioma (7 papers, 2016 to 2025). A benign or malignant brain and spinal cord tumor that arises from glial cells (astrocytes, oligodendrocytes, ependymal cells). "In glioma, the expression of miR-135b suppresses cell proliferation, invasion, and stem cell-like phenotypes by targeting SMAD5, ADAM12, and GSK3β." (PMID 39805813, 2025). "Our present study indicates that the repression of E-cadherin mRNA and protein expression via DAPT treatment in glioma cells is regulated by BMP-independent Smad5 activation." (PMID 34104086, 2021). "LN18 glioma cells were pretreated with control (siCL), Smad1 (siSmad1)-, or Smad5 (siSmad5)-specific siRNAs and then were kept as controls or treated with 80 μM DAPT for 48 h." (PMID 34104086, 2021). "LN18 glioma cells were pretreated with control (siCL), Smad1 (siSmad1)-, or Smad5 (siSmad5)-specific siRNA and then were kept as controls or treated with 80 μM DAPT for 48 or 96 h and then cell migration was examined by chemotaxis and wound-healing methods." (PMID 34104086, 2021). "It was shown that the gene knockdown of Smad5 significantly recovered the DAPT-promoted LN18 glioma cell migration compared to the cells-cotreating with control-specific siRNA and DAPT." (PMID 34104086, 2021). "Here, we aim to explore whether overexpression of Per2, a tumor suppressor gene, may inhibit the malignant phenotype of glioma based on regulating PTEN/AKT/Smad5/Id3 signaling pathway and would help to identify a novel target for clinical precision medicine." (PMID 35599595, 2022). "However, it was surprisingly found that DAPT and RO4929097 unexpectedly inhibited E-cadherin (not N--cadherin) mRNA/protein expression and consequently promoted glioma cell migration via BMP-independent Smad5 activation." (PMID 34104086, 2021). "In addition, γ-secretase activity inhibition was regulated by bone morphogenetic proteins-independent Smad5 activation in glioma cells." (PMID 34104086, 2021). "Moreover, the present results showed that only Smad5 could regulate E-cadherin expression in DAPT-treated glioma cells." (PMID 34104086, 2021). "This study reported that γ-secretase activity inhibition by DAPT/RO4929097 in LN18 and LN229 glioma cells promotes glioma cell migration by inhibiting E-cadherin mRNA and protein levels through BMP-independent Smad5 activation." (PMID 34104086, 2021). "The knockdown of Smad5 prevented DAPT-dependent repression of E-cadherin protein and mRNA levels in LN18 glioma cells compared to cells co-treated with control siRNA and DAPT." (PMID 34104086, 2021). "MiR-135 also downregulates the expression of SMAD5 and STAT6, inducing apoptosis in glioma cells." (PMID 39805813, 2025). "ADAM17 and MAML3 are indexed in the KEGG “Notch signaling pathway”, and BMP2 and SMAD5 are indexed in the KEGG “TGF-beta signaling pathway”, which confirms our data on the involvement of these processes in the formation of glioma neurospheres." (PMID 36231068, 2022). "We can exclude the possibility of autocrine BMP effects on DAPT-treated glioma cells because the BMP antagonist Noggin did not affect the repression of E-cadherin expression through Smad5 by DAPT treatment." (PMID 34104086, 2021). "(ii) This DAPT/RO4929097 effect on glioma cells is regulated by BMPs-independent Smad5 (not Smad1) activation." (PMID 34104086, 2021). "CEBPB might act in glioma by regulating CCL2, CCND1, THBS1, THBS2, SMAD5, SMAD6, TGFBR2, and TCF12." (PMID 27716259, 2016). "As a result, we assumed that SMAD5 and SMAD6 might affect glioma by regulating the TGFB signaling." (PMID 27716259, 2016).
hepatocellular carcinoma (7 papers, 2014 to 2026). A malignant tumor that arises from hepatocytes. "For instance, MALAT1 upregulated SMAD5 expression by reducing miR-142-3p expression in hepatocellular cancer, which facilitates cell growth and EMT23." (PMID 36635290, 2023). "The results showed that miR-139-5p and TGFBR3 were significantly down-regulated in hepatocellular carcinoma tissues, and miR-582-3p, ACVR2B, SMAD2 and SMAD5 were up-regulated in hepatocellular carcinoma tissues." (PMID 35386287, 2022). "The MALAT1-miR-142-3p-SMAD5 axis plays an important role in cell proliferation, migration, and invasion of hepatocellular carcinoma cells." (PMID 31168355, 2019). "Collectively, miR-142-3p suppressed migration, invasion, and EMT by targeting SMAD5 in hepatocellular carcinoma." (PMID 31168355, 2019). "MiR-142-3p suppressed cell proliferation migration, invasion and EMT, and promoted cell apoptosis by targeting SMAD5 in hepatocellular carcinoma." (PMID 31168355, 2019). "MiR-142-3p inhibited cell proliferation, migration, invasion and EMT, and promoted the cell apoptosis by targeting SMAD5 in hepatocellular carcinoma." (PMID 31168355, 2019). "In addition, miR-142-3p suppresses cell proliferation, migration, invasion and EMT, and promotes cell apoptosis by targeting SMAD5 in hepatocellular carcinoma." (PMID 31168355, 2019). "For example, in hepatocellular carcinoma, MALAT1 upregulates SMAD5 expression by sequestering miR‐142‐3p, which promotes epithelial–mesenchymal transition and enhances tumor cell proliferation and invasiveness." (PMID 41584724, 2026). "We selected 2 differentially expressed miRNAs (miR-139-5p and miR-582-3p) and four hub mRNAs (ACVR2B, SMAD2, SMAD5, and TGFBR3) for qRT-PCR verification in 20 hepatocellular carcinoma tissues and 20 adjacent tissues." (PMID 35386287, 2022). "In hepatocellular carcinoma patients, CSN5 depletion took effective effects through downregulation of SMAD5-related pathways including CENPA, which represented a potential target for therapeutic approaches." (PMID 32090070, 2020). "Mix.1 is induced in Xenopus embryos by BMP4 or activin A in a SMAD5-dependent manner, and MIXL1 can be induced by TGF-β in human hepatocellular carcinoma and in mouse embryonic stem cells." (PMID 25544748, 2014).
diffuse large B-cell lymphoma (6 papers, 2012 to 2021). "This inhibitory effect of miR-155 on SMAD5 was also found in primary rhesus macaque peripheral blood mononuclear cells with chronic simian immunodeficiency virus infection, a diffuse large B cell lymphoma cell line, and a lung epithelial cell line." (PMID 28473977, 2017). "Moreover, knockdown of SMAD5 by overexpressing the miR-155 expression enhanced the aggressiveness of diffuse large B cell lymphoma in vivo." (PMID 28629378, 2017). "Thus, down-regulation of SMAD5 in diffuse large B-cell lymphoma defines a unique mechanism used by the cancerous cells to escape TGFβ growth inhibitory effects." (PMID 23431463, 2013). "miR-155 renders diffuse large B cell lymphoma (DLBCL) cells resistant to the growth inhibitory effects of TGF-β1 and BMP by targeting Smad5." (PMID 26563372, 2016). "miR-155 targets c-Maf in lymphocytes, and HGAL and SMAD5 in diffuse large B-cell lymphoma (DLBCL)." (PMID 23431463, 2013). "In diffuse large B-cell lymphoma (DLBCL), miR-155, which is over-expressed in aggressive type of B-cell lymphoma, targets SMAD5 by binding to the 3′ UTR of the SMAD5 gene." (PMID 22943793, 2012).
keloid (5 papers, 2021 to 2023). An irregularly shaped, elevated mark on the skin caused by deposits of excessive amounts of collagen during wound healing. "Western blot analysis showed that lncRNA LINC01116 and SMAD5 were upregulated in keloids, while miR-203 expression was downregulated." (PMID 37705977, 2023). "To conclude, HOXA11-AS promote keloid formation and induced ColI synthesis through sponging miR-124-3p-mediated Smad5 signaling." (PMID 36046343, 2022). "A recent study showed that LINC01116 promoted keloid formation through regulating miR-203/SMAD5 axis." (PMID 36046343, 2022). "Furthermore, studies have shown that downregulating lncRNA LINC01116 inhibits keloid by regulating the miR-203/SMAD5 axis." (PMID 37705977, 2023). "Therefore, H19 promotes keloid progression via sponging miR-196b-5p and increasing SMAD5 expression." (PMID 36046343, 2022). "Previous studies have shown that Smad5 can be activated by the adsorption of miR-124-3p by HOXA11-AS and then participate in the generation of keloids." (PMID 34646842, 2021).